KRTAP19-5 (keratin associated protein 19-5)
Description:
In the hair cortex, hair keratin intermediate filaments are embedded in an interfilamentous matrix, consisting of hair keratin-associated proteins (KRTAP), which are essential for the formation of a rigid and resistant hair shaft through their extensive disulfide bond cross-linking with abundant cysteine residues of hair keratins. The matrix proteins include the high-sulfur and high-glycine-tyrosine keratins.
Synonyms: KAP19.5
Tractability: No criterion of Open Targets' tractability assessment is met for any kind of drug.
Gene: Protein-coding gene on chromosome 21 (30,501,657 to 30,502,141, reverse strand). Ensembl gene ENSG00000186977.
Pathways (Reactome):
Developmental Biology: Keratinization
Gene Ontology:
Molecular function: protein binding
Cellular component: cytosol
Genetic constraint (gnomAD): Loss-of-function variants: 2 observed, 1.37 expected, observed/expected ratio (o/e) 1.46, 90% interval 0.46 to 1.92. That is too few expected variants to judge how well the gene tolerates losing a copy. Missense variants: 91 observed, 101.19 expected, observed/expected ratio (o/e) 0.9, 90% interval 0.76 to 1.07. Synonymous variants: 44 observed, 42.61 expected, observed/expected ratio (o/e) 1.03, 90% interval 0.81 to 1.33.
Homologues: Orthologues: chimpanzee KRTAP19-5 (100% identical), rabbit KRTAP19-5 (53% identical).
Diseases named in the same sentence as KRTAP19-5 in open-access papers:
KRTAP19-5 is named in the same sentence as 3 diseases in open-access papers, as found by Europe PMC text mining. Sharing a sentence is not in itself a finding about the gene and the disease. The quoted sentences say what the papers report.
Cirrhosis (1 paper, 2012). A chronic disorder of the liver in which liver tissue becomes scarred and is partially replaced by regenerative nodules and fibrotic tissue resulting in loss of liver function. "The cytoskeleton (COMMD5, KRTAP19-5, LLGL1 and SNX17) related genes were down-regulated in cirrhosis (F4)." (PMID 22397681, 2012).
KRTAP19-5 also shares sentences with these, for which no sentence is quoted: cancer (1 paper); tumor (1).